IL4I1 (interleukin 4 induced 1)
Diseases named in the same sentence as IL4I1 in open-access papers (continued):
Sharing a sentence is not in itself a finding about the gene and the disease.
ovarian carcinoma (4 papers, 2021 to 2025). A malignant neoplasm originating from the surface ovarian epithelium. "Moreover, high levels of l-phenylalanine- and l-tyrosine-derived metabolites associated with interleukin 4 induced 1 (IL4I1) activity were found in ovarian cancer ascites samples." (PMID 36765849, 2023). "Notably, metabolite levels associated with IDO1 and IL4I1 activity were elevated in ovarian cancer ascites compared to plasma samples." (PMID 36765849, 2023). "Since active IL4I1 is sufficiently expressed in ovarian cancer patients to modulate ascitic PP and 4HPP levels, this would likely allow the enhanced production of Trp-derived AhR agonists by IL4I1." (PMID 36765849, 2023). "Further exploration of the implications of enhanced IL4I1 activity is warranted to pave the way for successful immunotherapeutic treatment of ovarian cancer patients." (PMID 36765849, 2023). "At baseline disease, we found that the activity of IDO1 was increased in ovarian cancer patients compared to healthy controls, whereas elevated activity of IL4I1 was also found in ovarian cancer ascites samples." (PMID 36765849, 2023). "Nonetheless, elevated metabolism of Phe and Tyr by IL4I1 strongly correlated with disease stage, suggesting a potential role for IL4I1 in ovarian cancer progression." (PMID 36765849, 2023). "Further exploration of the implications of enhanced IL4I1 activity in ovarian cancer is warranted to pave the way for new immunotherapeutic strategies in the treatment of this disease." (PMID 36765849, 2023). "Based on the elevated levels of PP and 4HPP found in the ascites of patients with stage IV compared to stage III disease, our data additionally indicate a correlation between IL4I1 activity and ovarian cancer progression." (PMID 36765849, 2023). "In vitro, IL4I1 has been shown to promote the proliferation, migration and invasion of various tumor cell types, including ovarian cancer cells." (PMID 36765849, 2023). "The elevated activity of both IDO1 and IL4I1 found in ovarian cancer patients therefore supports the hypothesis of IL4I1 as a potential resistance mechanism against IDO1 inhibition." (PMID 36765849, 2023). "To evaluate whether elevated metabolism of Phe and Tyr by IL4I1 is limited to ovarian cancer ascites, we analyzed pleural effusions from non-small cell lung cancer patients, which accumulate by similar mechanisms as ascites." (PMID 36765849, 2023). "IL4I1 therefore presents a potential therapeutic target for ovarian cancer, while its expression, activity or metabolite levels may also serve as a biomarker for disease progression." (PMID 36765849, 2023). "Finally, elevated metabolism of l-phenylalanine and l-tyrosine by IL4I1 correlated with disease stage, pointing towards a potential role for IL4I1 in ovarian cancer progression." (PMID 36765849, 2023). "In addition to IDO1 and IL4I1, enhanced ARG1 expression has previously been reported in the context of human ovarian cancer." (PMID 36765849, 2023). "Notably, the prevailing metabolic profile of ovarian cancer patients was characterized by an apparent lack of elevated IL4I1 activity on Trp, the common substrate of IDO1, TDO and IL4I1." (PMID 36765849, 2023).
viral infections (4 papers, 2021 to 2023). "ARV, ALV-J and MDV infection can cause avian immunosuppressive diseases, and IL4I1 expression was upregulated after each of these three viral infections." (PMID 38140587, 2023). "As SARS-CoV-2 may increase AhR ligands independently of IDO induction, it is proposed that SARS-CoV-2, like other viral infections, may be associated with the upregulation of IL4I1, and thereby with the driving of tryptophan to the production of other AhR ligands, viz I3P and I3A." (PMID 33562472, 2021). "Studies by high-throughput sequencing technology have found that a large amount of IL4I1 expression can be induced after a variety of viral infections." (PMID 38140587, 2023). "Many bacterial and viral infections have been shown to increase interleukin-4-induced 1 (IL4I1), especially in macrophages, with IL4I1 leading to the induction of other AhR ligands, especially via I3P production." (PMID 33562472, 2021). "Here, using a combination of biochemical and immunological methods, we show that IL4I1 indeed binds to the transmembrane protein TMPRSS13, a serine protease recently shown expressed and important in human cancers and in viral infections." (PMID 36131918, 2022).
chronic lymphocytic leukemia (3 papers, 2022 to 2023). "A recent study revealed that IL4I1 expression was enhanced in most tumor entities compared with that of normal tissues, and IL4I1 is a metabolic immune checkpoint, thereby suppressing adaptive immune responses and promoting chronic lymphocytic leukemia progression." (PMID 36866272, 2023). "IL4I1 can activate aryl hydrocarbon receptor (AHR) and promote progression of cancer by enhancing chronic lymphocytic leukemia progression." (PMID 35778697, 2022).
diffuse large B-cell lymphoma (3 papers, 2021 to 2025). "Zhang R, Zhang Y, Xiao H, Liu Q, Zhao M. Knockout IL4I1 affects macrophages to improve poor efficacy of CD19 CAR-T combined with PD-1 inhibitor in relapsed/refractory diffuse large B-cell lymphoma." (PMID 41219641, 2025). "Moreover, whereas high IL4I1 expression appears to portend a poor prognosis in several solid tumor types, high levels of IL4I1 are correlated with superior outcome in follicular and diffuse large B-cell lymphoma." (PMID 39211039, 2024).
head–neck cancer (3 papers, 2021 to 2025). "For Il4I1 there is only a single study so far that investigated the role of IL4I1 in head–neck cancer-derived mesenchymal stromal cells (MSC) in the microenvironment." (PMID 40332319, 2025). "In this study, we show that mesenchymal stromal cells derived from head–neck cancer express the amino acid oxidase IL4I1 that has been detected in different types of tumor cells." (PMID 34068423, 2021).
lung carcinoma (3 papers, 2023). "We further knock down IL4I1 in Lewis lung cancer (LLC) cells to investigate the role of IL4I1 in sensitizing the PD‐1 blockade in an orthotopic LUAD murine model." (PMID 37655051, 2023).
lymphoma (3 papers, 2021 to 2025). A malignant (clonal) proliferation of B- lymphocytes or T- lymphocytes which involves the lymph nodes, bone marrow and/or extranodal sites. "The drug-resistant lymphoma lines reported in this study have been shown to favor OXPHOS for energy production, so a reduction in IL4I1 expression may hold the key to this metabolic adaptation." (PMID 33946867, 2021).
autoimmune disease (2 papers, 2023 to 2024). A disorder resulting from loss of function or tissue destruction of an organ or multiple organs, arising from humoral or cellular immune responses of the individual to their own tissue constituents. "The genes encoded by IL4I1 are located in the susceptible regions of various autoimmune diseases and are mainly expressed in human immune cells." (PMID 37143094, 2023). "It is speculated that IL4I1 may be closely related to the occurrence of autoimmune diseases." (PMID 37143094, 2023).
bladder cancer (2 papers, 2022 to 2024). "Nevertheless, a precise understanding of the correlation of IL4I1 with immunological features and immunotherapy efficacy in bladder cancer (BLCA) remains incomplete." (PMID 38873416, 2024). "We obtained the results of immunohistochemical staining of ACOT13, CYP1, DECR1, IL4I1, and SCD in both normal tissues and bladder cancer tissues and found that the expression of CYP1 was higher in normal tissues, while other genes were higher in tumor tissues than in normal tissues." (PMID 36131793, 2022).
diabetes (2 papers, 2021 to 2024). "The human IL4I1 gene is located on chromosome 19q13.3-13.4, aregion implicated in susceptibility to systemic lupus erythematosus, rheumatoidarthritis, multiple sclerosis, and insulin-dependent diabetes mellitus, raisingthe possibility that IL4I1 may play a role in inflammatory diseases." (PMID 39355609, 2024).
follicular lymphoma (2 papers, 2019 to 2025). Follicular lymphoma is a form of non-Hodgkin lymphoma characterized by a proliferation of B cells whose nodular structure of follicular architecture is preserved. "This may explain why IL4I1 expression in patients with follicular lymphoma is associated with parameters indicative of a good prognosis." (PMID 31330829, 2019). "However, in some tumors, such as follicular lymphoma, increased expression of IL4I1 may be associated with effective immune responses to tumors, reflecting a better prognosis." (PMID 41008831, 2025). "In follicular lymphoma, the presence of IL4I1 probably results from the persistence of its physiological expression in centrocytes and may thus contribute to limiting proliferation of the tumor cells." (PMID 31330829, 2019).
head and neck squamous cell carcinoma (2 papers, 2023 to 2025). A squamous cell carcinoma that arises from any of the following anatomic sites: lip and oral cavity, nasal cavity, paranasal sinuses, pharynx, larynx, and salivary glands. "In head and neck squamous cell carcinoma, IL4I1 was confirmed to inhibit T cell proliferation." (PMID 36866272, 2023).
hepatocellular carcinoma (2 papers, 2020 to 2024). A malignant tumor that arises from hepatocytes. "A recent investigation identified indole 3-pyruvate (I3P), a tryptophane metabolite created by the enzyme interleukin 4-induced 1 (IL4I1), as an additional AHR ligand and driver of tumor growth in hepatocellular carcinoma." (PMID 39061522, 2024).
sarcoma (2 papers, 2024 to 2025). A usually aggressive malignant neoplasm of the soft tissue or bone. "In sarcoma immunoradiotherapy, elevated tumour‐associated macrophages (TAMs) expressing IL4I1/HES1 predict poor response, highlighting the need for combinatorial approaches targeting monocyte–macrophage axes." (PMID 40936181, 2025).
serous ovarian cancer (2 papers, 2023). "In a single‐cell study of IL4I1 in serous ovarian cancer, Kaplan–Meier curve analysis showed that higher IL4I1 expression was associated with poor OS." (PMID 38062922, 2023). "The current study provides indications for a role of IL4I1 in high-grade serous ovarian cancer, although these findings should be validated in a larger patient cohort." (PMID 36765849, 2023). "Our findings demonstrate enhanced amino acid metabolism by IDO1/TDO and IL4I1 in high-grade serous ovarian cancer patients, with markedly elevated metabolite levels in patient ascites samples compared to patient and healthy donor plasma." (PMID 36765849, 2023). "Moreover, the enzymes IDO1 and IL4I1 were identified as active players in high-grade serous ovarian cancer, and a correlation between IL4I1 metabolite levels and disease stage was revealed." (PMID 36765849, 2023). "Our data suggest a role for both IDO1 and IL4I1 in high-grade serous ovarian cancer and indicate that IL4I1 may be involved in progression of the disease through metabolism of Phe and Tyr." (PMID 36765849, 2023). "Although Trp metabolism by IL4I1 does not appear enhanced in high-grade serous ovarian cancer patients, this does not exclude an elevated metabolism of other substrates by IL4I1." (PMID 36765849, 2023).
acute myeloid leukemia (1 paper, 2024). Acute myeloid leukemia (AML) is a group of neoplasms arising from precursor cells committed to the myeloid cell-line differentiation. "For example, Sirt2 has been implicated in the control of IL4i1 expression in blood cells from acute myeloid leukemia (AML)." (PMID 38605962, 2024).
acute myocardial infarction (1 paper, 2024). Necrosis of the myocardium, as a result of interruption of the blood supply to the area. "Moreover, our research group discovered that IL4I1 mediates thesuppressive effects of CD4+LAP+ Tregs in the context of atherosclerosis, a commoncause of acute myocardial infarction." (PMID 39355609, 2024).
allergic rhinitis (1 paper, 2025). Inflammation of the nasal mucous membranes caused by an IgE-mediated response to external allergens. "Recent studies have indicated that pollutants alter IL4I1 expression, impacting sperm motility, while macrophage-derived IL4I1 worsens allergic rhinitis by promoting nasal EMT." (PMID 40559961, 2025).
Autoimmunity (1 paper, 2019). The occurrence of an immune reaction against the organism's own cells or tissues. "Manipulating IL4I1 in vivo thus opens new avenues for the treatment of autoimmunity and cancer." (PMID 31330829, 2019).
endometrial cancer (1 paper, 2025). Primary or metastatic malignant neoplasm involving the endometrium (mucous membrane that lines the endometrial cavity). "In endometrial cancer (EC), IL4I1 expression was significantly higher than that in normal endometrial tissues." (PMID 41008831, 2025). "Based on the single-cell RNA-seq data from GSE139555, we investigated the expression profile of IL4I1 within the endometrial cancer (EC) microenvironment." (PMID 41008831, 2025). "Given the importance of immune evasion and inflammation in endometrial cancer metastasis, IL4I1 may represent a novel candidate for further exploration as a therapeutic target." (PMID 41008831, 2025).
endometrioid adenocarcinoma (1 paper, 2025). An adenocarcinoma characterized by the presence of malignant glandular epithelial cells resembling endometrial cells. "Notably, serous endometrial carcinoma, which has the poorest prognosis, exhibited the highest IL4I1 expression, whereas endometrioid adenocarcinoma, associated with a better prognosis, showed only slightly elevated IL4I1 expression compared to normal endometrial tissues." (PMID 41008831, 2025).
endometriosis (1 paper, 2023). The growth of functional endometrial tissue in anatomic sites outside the uterine body. "Moreover, positive expression of IDO1, TDO2 and IL4I1 was related to advanced stage, metastasis, bilateral tumours, endometriosis and tumour rupture (p < 0.05) respectively." (PMID 38062922, 2023).
hypopharyngeal carcinoma (1 paper, 2025). Carcinoma, predominantly squamous cell, arising from the epithelial cells of the hypopharynx. "Hypopharyngeal carcinoma, p16-negative OPSCC, and p16-positive OPSCC demonstrated low Il4I1 expressions more often." (PMID 40332319, 2025).
influenza infection (1 paper, 2019). "Genes such as HEATR9, IL4I1, TNFSF13B (BAFF), and PDCD1 (PD-1) are recently implicated in influenza pathogenesis and mucosal defense, thereby signifying the role of the nasal epithelium against influenza infection." (PMID 31461941, 2019).
liver cancer (1 paper, 2024). An epithelial or non-epithelial malignant neoplasm that arises from the liver. "We examined the ability of the first downstream metabolite in each of the Trp metabolism pathways for their ability to rescue the growth of Trp-starved liver cancer cells: these are Kyn, 5HTP (a cell permeable intermediate of serotonin) and I3P, which is the first indole generated by IL4I1." (PMID 38769298, 2024).
lymph node metastases (1 paper, 2023). "The increment of IL4I1 mRNA expression was related to high-grade malignancy, lymph node metastases and extrathyroidal extension." (PMID 37434155, 2023). "The upregulated IL4I1 mRNA expression is positively related to lymph node metastasis, high TNM stage and extrathyroidal extension." (PMID 37434155, 2023).
lymphocytic leukemia (1 paper, 2022). "A recent study showed a strongly association between high IL4I1 levels and an accumulation of myeloid-derived suppressor cells and Tregs in lymphocytic leukemia (CLL)." (PMID 35962343, 2022).
nasal polyp (1 paper, 2025). "This study aims to investigate how PM2.5 stimulates human nasal mucosal epithelial cells, activates IL4I1, modulates AhR expression, and induces nasal mucosal damage and tissue remodeling, thereby contributing to nasal polyp formation." (PMID 40559961, 2025). "We elucidated how PM2.5 stimulates human nasal mucosal epithelial, activate IL4I1, modulates AhR expression, and induces nasal mucosal damage and tissue remodeling, ultimately contributing to nasal polyp formation." (PMID 40559961, 2025). "Murine models further confirmed that PM2.5 exacerbated nasal polyp formation and tissue remodeling via the IL4I1-AhR pathway." (PMID 40559961, 2025).
Obesity (1 paper, 2021). Accumulation of substantial excess body fat. "Diet is known to regulate IL4I1, suggesting that dietary factors contributing to obesity and T2D may be acting in part via the upregulation of IL4I1 and I3P." (PMID 33562472, 2021).
osteosarcoma (1 paper, 2022). A usually aggressive malignant bone-forming mesenchymal neoplasm, predominantly affecting adolescents and young adults. "However, IL1B_TAM and FCN1_TAM cells also positively expressed the M2‐TAM signature genes, including MRC1, CD206, MS4A4A and IL4I1, suggesting that they were undergoing the transition into M2‐TAM in osteosarcoma TME." (PMID 36305631, 2022).
ovarian tumors (1 paper, 2021). "In the current research, prognostic IL4I1 was higher in ovarian tumors compared to the normal ovary." (PMID 34717685, 2021).
Pleural effusion (1 paper, 2023). The presence of an excessive amount of fluid in the pleural cavity. "Overall, lower PP and 4HPP levels were detected in the pleural effusion compared to the ascites samples, despite the relatively similar IL4I1 levels." (PMID 36765849, 2023). "Similar to the ascites samples, PP and 4HPP levels in the pleural effusion samples were strongly correlated with each other, while 4HPP levels also significantly correlated with the levels of IL4I1." (PMID 36765849, 2023).